CD4 (CD4 molecule)
Diseases named in the same sentence as CD4 in open-access papers (continued):
Sharing a sentence is not in itself a finding about the gene and the disease.
infection (continued). "The infection efficiency was measured by infecting naïve CD4+ T cells with a control lentivirus expressing GFP (69% infection efficiency)." (PMID 22859956, 2012). "There is compelling evidence from human studies that HCMV-infection leaves a unique signature on the CD8+ T cell compartment but less so for the CD4+ T cell compartment." (PMID 22916013, 2012). "The natural history of infection with the human immunodeficiency virus (HIV) is characterized by a progressive decline of T helper (CD4+) lymphocytes." (PMID 23251108, 2012). "major immune response we monitored the expression of the CCR6 ligand CCL20 and the number of CD4+CCR6+ cells in the draining lymph nodes during the early phase of infection in B6.WT mice." (PMID 23028548, 2012). "Six weeks after infection, 26.23±3.05% of CD4+ T cells and 30.03±4.43% of CD8+ T cells expressed the HIV coreceptor." (PMID 22675567, 2012). "As a consequence, up to 60% of CD4+ T cells in the lamina propria of the lower gastrointestinal (GI) tract are lost as early as 2–4 wk after infection." (PMID 22319447, 2012). "Before infection three infected mice had average CD4 count of 672±96.08 cells/μl, but it decreased significantly (493.33±72.34 and 358.66 cells/μl) 25 and 50 days after infection." (PMID 22675567, 2012). "Cell-free viruses harvested 3 or 4 days after infection were sequentially passaged four times to fresh CD4+ T cells." (PMID 23110705, 2012). "Effector CD4 T cells can be generated during both chronic and acute infection with herpesviruses infection, and are important for controlling the infection through both cytotoxic and cytokine-dependent mechanisms." (PMID 23012630, 2012). "Uninfected DCs capture HIV-1 and mediate viral transfer to bystander CD4+ T cells through a process termed trans-infection." (PMID 23271952, 2012). "It is also interesting that in a small subset of macaques with available cryopreserved samples, we detected a significant association between pre-infection NKT frequencies and preservation of CD4+ T cells post SIV infection." (PMID 23028326, 2012). "The early post-vaccination CD8+ and CD4+ T-cell responses were broad but the anamnestic post-infection responses were narrow, perhaps an indicator of why there was no control of virus replication." (PMID 23025660, 2012). "Infection induced significant increases in CD4+ and activated CD4+ T-cells in the lungs of Wt and all TLR−/− groups, compared to sham inoculated controls." (PMID 22724018, 2012). "We therefore analyzed splenocytes using flow cytometry and found that injection of MSCs after infection with CVB3 led to an increased number of CD4+ and CD8+ T cells compared to the untreated mice." (PMID 22815907, 2012). "Recently, we analyzed HLA-DR1 transgenic (DR1) mice and C57BL/10 (B10) mice after infection with influenza virus A/New Caledonia/20/99 (NC) and defined epitopes recognized by virus-specific CD4 T cells." (PMID 22457834, 2012). "Where T cell subset analysis was possible, we showed that genotype-3a NS proteins were targeted exclusively by CD8 T cells in chronic infection, whereas in resolved infection CD4 T cells were also detected." (PMID 22337948, 2012). "DCs efficiently capture HIV-1 but captured HIV-1 partly escapes from degradation and fully infectious virus particles are subsequently presented to CD4+ T-lymphocytes, thereby efficiently infecting these target cells (trans-infection)." (PMID 22412885, 2012). "When analyzing the percentage of TFH cells within the CD4+CD44hi gate, dLNs exhibited the highest level compared to the other organs at days 8 and 12 post-infection." (PMID 22792401, 2012). "In the spleen, 14 days after infection the number of CD4+, CD8+ and γδTCR+ cells returned to numbers similar to uninfected controls." (PMID 22428026, 2012). "LewisX and MUC1 isolated from breast milk have been shown to inhibit binding of cell-free HIV-1 to DC-SIGN and to prevent transfer of infection to CD4+ T cells." (PMID 22952771, 2012).
infection (continued). "Univariate analyses revealed three factors associated with infection by CXCR4-using viruses: the current CD4-cell count, the nadir CD4-cell count and current treatment with protease inhibitors." (PMID 23226258, 2012). "The effects of JES6-1 treatment in vitro drastically change during the infection in which inhibition of CD4+ T cell response to parasites is observed at the chronic phase of the disease, but not at the acute phase." (PMID 22272258, 2012). "CD4+T helper (Th) cells are the master regulators of adaptive immune responses that control different types of pathogen infections and regulate disease progression." (PMID 23227158, 2012). "Our analyses are in agreement with early studies in humans suggesting that latent reservoirs in resting CD4+ T cells are laid down earlier in infection and are extremely long-lived." (PMID 22496643, 2012). "The role of T cells in control of infection has been extensively studied and it is clear that both CD4+ and CD8+ T cells contribute importantly to disease outcome." (PMID 23181064, 2012). "It has been shown that mAbs specific for α4β7 partially and transiently inhibit infection of α4β7-positive CD4+ T cells by HIV-1/SF162 at low inocula." (PMID 22693444, 2012). "Several studies have shown that co-production of IL-10 by IFN-γ producing CD4+ Th1 cells is critically important for regulation of excessive Th1 and inflammatory responses in many infections." (PMID 22860150, 2012). "This is true and a matter of debate, but our data showed a significant decrease in the number of CD4+CD25+ Foxp3+ Treg cells that was sustained up to week 10 of infection." (PMID 23226464, 2012). "The expression of HLA-DR was observed on 2.50±0.81% of CD4+ T cells and 3.00±0.80% of CD8+ T cells before infection and jumped to 39.28±2.90% (n = 4) and 49.98±2.24% (n = 4) respectively for CD4+ and CD8+ T cells after infection." (PMID 22675567, 2012). "Of the 250 simulations not a single case of X4 emergence was observed when therapy was applied at any stage of infection, with all patients experiencing increases in CD4+ T cell counts under this therapy." (PMID 22866173, 2012). "Several recent studies support a model that involves two steps prior to productive infection of CD4+ T cells." (PMID 23109932, 2012). "Strikingly, inhibition of cell-cell transmission by CD4-IgG2 required an approximately 40-fold higher 50% inhibitory dose (IC50) than inhibition of the same virus strain during cell-free infection." (PMID 22496655, 2012). "We found that mice deficient in either CD4+ or CD8+ cells maintained normal liver function and survived LCMV-13 infection." (PMID 23300439, 2012). "Studies using the SIV model of infection have demonstrated the critical role of CD4+ CM cells in the pathogenesis of HIV disease." (PMID 23185351, 2012). "We suggest that the HH genotype provides partial protection against infection possibly related to heightened peripheral blood CD4 cell numbers in carriers of this genotype." (PMID 22412885, 2012). "Our data also showed a correlation between the amounts of triple positive IL-2+TNFα+IFNγ+ vaccine-specific CD4 T cells induced by immunization and the subsequent level of protection against infection with M.tb." (PMID 22768165, 2012). "Over the chronic phase of infection, the viral load remains stable, whereas CD4+ T cell levels gradually decline." (PMID 22754568, 2012). "WT/GKO recipients treated with anti-IFN-γ succumbed to infection by day nine p.i. similar to infected recipients of GKO CD4+ T cell." (PMID 22642802, 2012). "As compared to its value before infection, the median blood CD4+ T-cell count reached its lowest value on 11–12 dpi (76.9% decrease, p = 0.0004), coincident with the peak in viral load." (PMID 22632376, 2012). "CD4+ T cells have enhanced responses after infection or immunization, are resistant to suppressor activity mediated by a subset of CD8+ T cells, but are more susceptible to NK cell lysis." (PMID 22905720, 2012).
infection (continued). "At thirty days post infection, comparable frequencies of gp61-specific CD4 T cells were found in CreNEG, cHET and cKO mice." (PMID 22912696, 2012). "In mouse, CD4+ and CD4− pDC have been identified with CD4− pDC being the major source pDC subset that migrate into lymph nodes in response to infection." (PMID 22428075, 2012). "We next asked how the quality of the B cell response after PR8 infection related to the pattern of cytokines produced by virus-specific CD4 T cells." (PMID 22457834, 2012). "After establishing the effect of LAI infection on peripheral blood CD4+ T cell levels, we evaluated its effect on CD4+ cell depletion in lymph nodes, spleen and in the human thymic organoid (HTO)." (PMID 22640559, 2012). "The importance of Notch signaling during CD4+ Th1 differentiation and its correlated resolution of pathogen infection is currently unclear." (PMID 22396647, 2012). "The resolution of the infection in the liver is attributed to the development of a Th1-dominated granulomatous response, characterized by high IFNγ production by CD4 T cells." (PMID 21811511, 2012). "Here we demonstrate that infection of BALB/c mice with respiratory syncytial virus (RSV) induced IL-10 production by CD4+ and CD8+ T cells in the airways at later time points (e.g. day 8); a proportion of these cells also co-produced IFN-γ." (PMID 22393401, 2012). "Multiple miRNAs are positively or negatively correlated with peripheral blood CD4+ T-cell count, and miRNA expression changes cannot be explained solely by declines in the CD4+ population during infection." (PMID 22240256, 2012). "HPV16/16-like infection was least likely to clear at low CD4 cell count (<200 cells/mm3) than other HPV groups (see Figure." (PMID 22292027, 2012). "Infection of primary CD4+ T cells was strongly enhanced when they were co-cultured with HIV-1 pulsed mDCs (filled bars)." (PMID 22545022, 2012). "This is consistent with the survival result showing that, at this time point, the majority of B−/− mice, but few wild-type or CD4−/− mice, succumbed to death after infection." (PMID 23133489, 2012). "The robust replication of HIV-1 following infection of activated CD4+ T cells and the accompanying immune response is cytopathic." (PMID 24832049, 2012). "In particular, the contribution of CD8+ T cells was substantially greater to that of CD4+ T cells, which is consistent with their reported role in the rapid resolution of secondary infection in re-challenged and vaccinated mice." (PMID 22470440, 2012). "CD4 T cells purified from the mediastinal lymph node (MedLN) and spleen on day 10 after NC infection of DR1 mice were tested for their ability to secrete IL-2, IFN-γ, or IL-4 after stimulation with defined peptide epitopes." (PMID 22457834, 2012). "Claudin 7 is involved in the infection of CD4(-) cells through HIV-1 and the HIV-1 Tat protein is held to be responsible for an increased permeability of the BBB by influencing claudins." (PMID 23284715, 2012). "It is possible that IFN-γ and IL-10 are produced at the sites of infection, as observed in leishmaniasis, as a result of local recruitment and accumulation of activated CD4+ T cells in the perivascular area adjacent to infected ECs." (PMID 21912565, 2012). "After primary infection, CD4+IL-4+ T cells disseminate around the body to lymphoid and nonlymphoid organs, such as airways, peritoneal cavity, and liver, and have a lower apoptotic potential." (PMID 23053394, 2012). "There was also a decrease in CD4+ T-cell numbers 5 days after infection, followed by an increase on days 14–21." (PMID 23119083, 2012). "The GALT is a major site for HIV replication in vivo, with HIV-specific CD4+ T-cells being highly permissive to infection." (PMID 22470433, 2012). "For this reason, CD4+CD25+ T cells were monitored during our study to understand their role during infection." (PMID 23216686, 2012).
infection (continued). "Considering this, if the preferential infection of SupT1 cells didn't prevent infection of primary CD4+ T cells, the killing of primary cells would be shown." (PMID 22701517, 2012). "The capacity of the gp41-directed agents to block infection post CD4 recruitment, is in line with previous reports observing MPER mAbs and HR1 and HR2 targeting inhibitors which act at a prefusion stage." (PMID 22496655, 2012). "A previous study showed that an early T cell-mediated immune response is developed in mice upon infection with M. ulcerans, with migration of pathogen-specific CD4+ T cells from the DLN to the site of infection." (PMID 22393444, 2012). "In our study, we have found an increase of spleen CD4+ T lymphocytes producing IL-10 seven days after infection, in addition to the IFNγ and TNF-α producing cells." (PMID 22666132, 2012). "One study to date has demonstrated iNKT cell culture supernatant inhibition of HIV p24 production during in vitro CD4+ T cell infection, which was shown to be IFNγ-dependent." (PMID 22916008, 2012). "Potentially confounding effects of sex and age on the analysis notwithstanding, there was a significant correlation between infection intensity and the proportions of CD200Rhi CD4 T cells in blood." (PMID 22496920, 2012). "The opposite was observed in the infection with BT forms, where initially there was an increase of CD4+ and CD8+ TNF-α, and only later of T-cells IFN-γ+." (PMID 22412949, 2012). "Antigen-specific CD4+ T cells are detected at only low levels at other stages of infection, except in sub-populations of individuals capable of controlling their infection naturally, referred to as long-term non-progressors (LTNP)." (PMID 22754568, 2012). "increasing numbers of CXCR4-expressing activated naive CD4+ T cells with declining total CD4+ T cell counts, thereby providing increased numbers of activated target cells for productive infection by X4 virus." (PMID 22866173, 2012). "A vast number of cells are lost during primary infection, and by the time the infection has reached a chronic stage; more than 50% of the CD4+ cells in the LN are lost." (PMID 22474480, 2012). "While early models focused on direct infection as a driver of CD4+ T cell depletion, it is clear that the majority of cell death during chronic infection is caused by indirect effects, including generalized T cell activation and apoptosis." (PMID 23209754, 2012). "DC-SIGN is also required for the formation of the infectious synapse between DC and T-lymphocyte during trans-infection of CD4+ T-lymphocytes with HIV-1 and DC-SIGN binding of neutralized virus can result in removal of neutralizing antibodies." (PMID 22412885, 2012). "Combined data sets from S1 extended over a two-year period from about 3 to 5 years of age/infection, when CD4 T cells ranged between 25% to 30% and viral set point was about 10,000 copies." (PMID 23244298, 2012). "We induced CCR5 to maximal levels and induced CD4 to high or low expression levels (relative to primary human CD4+ T cells) prior to infection." (PMID 22693444, 2012). "This phenomenon (linked to the virulence of Brucella strains and to the severity of the infection) is consistent with the observed pathological changes of the spleen and suggests some inhibitory action related to the presence of regulatory CD4 + CD25+ T cells." (PMID 22500859, 2012). "HIV can enter quiescent CD4+ T cells, but the processes of reverse transcription and integration are inefficient and often result in abortive infections." (PMID 23029309, 2012). "We, as other authors, considered those individuals reading as recent HIV infections by BED-CEIA but with CD4<200 cells/μl or VL<400 copies/mL as false recent infections." (PMID 22363755, 2012). "To address this question, we studied untreated HIV-1-infected individuals who had progressed to advanced or severe immunologic stages of infection, with high viral loads and low CD4+ T cell counts." (PMID 22879884, 2012).
infection (continued). "Seven days after infection, we analyzed the cytokine production of antigen-specific CD4+ and CD8+ T cells following short-term in vitro peptide re-stimulation." (PMID 23115618, 2012). "Mice with single inactivation of N1 or N2 in their T cells were resistant to infection and developed a protective Th1 immune response, showing that CD4+ T cell expression of N1 or N2 is redundant in driving Th1 differentiation." (PMID 22396647, 2012). "Taken together, these data establish that IL-10 differentially affects T cell populations during the acute phase of infection; while it profoundly inhibits virus-specific CD4 T cell response it has only a minor impact on MCMV-specific CD8 T cell responses." (PMID 22876184, 2012). "Previously, it was also reported that antigen-specific CD4+ T cells are rapidly deleted from blood after infection with several pathogens such as Anaplasma marginales, Plasmodium, and Brugia Pahangi." (PMID 22905277, 2012). "Purified CD4 T cells from the MedLN on day 10 after PR8 infection were tested for their ability to produce cytokines after stimulation with peptides known to be strong epitopes in NC and conserved between NC and PR8." (PMID 22457834, 2012). "T cell phenotypes were compared between infected (HIV p24+) and uninfected (HIV p24-) CD4+ T cells from infection cultures (n = 12)." (PMID 23029309, 2012). "DC-SIGNR serves as an HIV-1 ligand to facilitate HIV-1 virion infection into adjacent CD4+T cells in trans and has been the subject of many recent studies." (PMID 22957026, 2012). "Our results indicate that these infections trigger a virus-specific immune modulation biased mainly towards macrophage and T CD4+ and B cell functions." (PMID 22229039, 2012). "Significantly higher CD4 count (median = 648 versus 221 cell/mL, p<0.001) substantiated the earlier stage of infection of recently infected women as compared to the rest of the study population." (PMID 22905148, 2012). "Thereafter, the two groups of CD4+ T cells were transplanted into either naïve mice) or mice at days 6 post-infection with wt." (PMID 23110112, 2012). "Expressed on dendritic cells, DC-SIGN and several other lectins are capable of binding Env and boosting infection in vitro by facilitating trans-infection of surrounding CD4 T cells by dendritic cell-bound virions." (PMID 22470838, 2012). "These values fell within close range of the confidence interval of the prevalence of recent infections determined using CD4<200 cells/μl and VL<400 copies/mL as surrogates of FPR [11.58%, (95% CI 8.89–14.74)]." (PMID 22363755, 2012). "Infection with Salmonella enterica is controlled by CD4 T cells making a predominantly Th1 response which persists for several weeks." (PMID 22496920, 2012). "The aim of this study was to characterize the in vivo plasma concentrations of the cytokines TNF-α, IFN-γ, IL-4, IL-10 and the overall role of CD4+ T cells in the development of cytokine levels during a primary infection." (PMID 22533922, 2012). "Resolution of productive infection (versus only carriage of the virus) is further supported by the down-regulation of CD4 only observed in the capsid high population." (PMID 22685410, 2012). "The depletion of CD4+ T cells after the onset of infection resulted in significantly increased numbers of Salmonella bacteria, whereas CD8+ T cell depletion did not." (PMID 22912884, 2012). "In general, biodiversity among the six subjects appeared unrelated to viral levels in plasma or cells, length of infection, or CD4 T cell levels, but revealed patterns of complexity within viral quasispecies in different host environments." (PMID 23244298, 2012). "By comparison, 6 days after infection all PBMC cultures showed complete eradication of primary CD4+ T cells." (PMID 22701517, 2012).